CD4 (CD4 molecule)
Diseases named in the same sentence as CD4 in open-access papers (continued):
Sharing a sentence is not in itself a finding about the gene and the disease.
Autoimmunity (continued). "It should also be noted that we switched to the distal Lck-cre deletion strain, which is superior to the CD4-cre strain because of a small number of TGF-βR+ ‘escapees’ that differentiate into nTreg during neonatal development and prevent autoimmunity in these mice." (PMID 25569154, 2015). "By crossing IL-2Rα−/− mice with CD4 knockout and CD8 knockout mice, we demonstrated that CD8+ T cells mediate biliary ductular damage whereas CD4+ T cells mediate induction of colon-specific autoimmunity." (PMID 25133396, 2014). "Recent findings have shown the CD4+ T-cell-mediated immune surveillance in the cochlea, but the initial step of the autoimmunity or antigen presentation has not yet been elucidated in the cochlea, in which a drainage lymph node has not been found." (PMID 25566079, 2014). "By restricting the genetic defect (TR2-deficiency) to mature CD4+ T cells, we show that TGF-β signalling is not essential for the suppression of autoimmunity." (PMID 24115907, 2013). "Similarly, although CD4+Foxp3+ Tregs are known to control lymphoproliferation and autoimmunity, examination of LPR lymph node CD4+ T cells revealed that FcRγ-expressing cells were distinct from the Foxp3+ population." (PMID 23762329, 2013). "Absence of STAT1 results in impaired CD4+CD25+ Treg development and increases host susceptibility to autoimmunity." (PMID 23935597, 2013). "An absence of PD-1 expression on forkhead box P3 (FOXP3) + CD4+ T cells greatly reduces their ability to suppress the activity of effector T cells, which is essential if self-tolerance is to be maintained and autoimmunity to be prevented." (PMID 24229326, 2013). "If not adequately regulated, CD4 T cells can be also involved in autoimmunity, asthma, and allergic responses." (PMID 23874332, 2013). "CD4+CD25+Foxp3+ regulatory T cells (Tregs) are essential in the induction and maintenance of immune tolerance and therefore play a critical role in the prevention and inhibition of inflammation and autoimmunity." (PMID 23977081, 2013). "Therefore, the occurrence of selective U94-specific CD4+ and CD8+ T cell responses in HT patients, suggests a specific role of this viral product as a potential trigger of autoimmunity." (PMID 23055929, 2012). "Anti-CD4 MAbs have been evaluated both in pre-clinical non-human primate models of transplantation and autoimmunity, as well as in clinical studies." (PMID 21818308, 2011). "Unlike other disease models that utilised Treg cell-depleted polyclonal T cells from wildtype mice to induce autoimmunity, it was not necessary to remove Treg cells from H/Kα−/− CD4+ T cell population for the induction of severe autoimmune gastritis." (PMID 22096532, 2011). "This higher expression of CD4+ NKT cells could potentially protect these patients from opportunistic mycobacterial infections and could impact autoimmunity." (PMID 20844745, 2010). "Thus, IL-2 in the form of an immune complex can efficiently substitute for CD4 help, promoting the differentiation of CTL capable of overcoming self-tolerance and inducing autoimmunity under lymphopenic conditions." (PMID 20856822, 2010). "Like p524-expanded CD4+CD25+ T cells, p570-expanded CD4+CD25+ T cells actively inhibited diabetes transfer to NOD.scid mice, and the transfer of 1×106 p570-stimulated CD4+CD25+ T cells was sufficient to prevent overt autoimmunity in young NOD mice." (PMID 19759824, 2009). "Indeed, patients with ICI-T1DM had a more robust Tfh cell response than those without IrAEs, with increased CD4+ICOS+PD-1hiCXCR5+ cells compared with controls without autoimmunity (P < 0.05)." (PMID 40626363, 2025). "Another factor that might contribute to the lack of overt spontaneous autoimmunity in Lrp10−/− mice is that CD4 T cells are not affected as much as CD8 T cells." (PMID 38956225, 2024).
Autoimmunity (continued). "We base this conclusion on transcriptome and proteome analysis of TNFR2- and CD28-costimulated CD4+ tTregs and conventional T cells (Tconvs), followed by bioinformatic comparison with published transcriptomic Treg signatures from NLT and LT in health and disease, including autoimmunity and cancer." (PMID 38341270, 2024). "Similarly, when TβRII is deleted in CD4+ T cells, mice develop lethal inflammation and multi-organ autoimmune inflammatory infiltration, however the role of TβRIII in autoimmunity is not yet described." (PMID 36855628, 2023). "However, other studies have found no significant changes in CD4 Treg in relation to disease severity or the presence of autoimmunity." (PMID 38259469, 2023). "However, we have studied theTgfbr3fl/fl.CD4Cre mouse, which lacks TβRIII in all CD4+ T cells, and this mouse does not develop spontaneous autoimmunity up to 18 months of age, data not shown." (PMID 36855628, 2023). "However, in general, there is still a lack of consensus on how CD4 Treg relate to the pathophysiology of CVID and its association with autoimmunity." (PMID 38259469, 2023). "However, there are several key clinical differences: CD40/CD40L deficiency results in severe opportunistic infections (due to defects in CD4+ T cell–mediated myeloid cell activation), while patients lacking AID, UNG, or CTNNBL1 exhibit follicular hypoplasia and autoimmunity." (PMID 37273190, 2023). "The importance of Treg cells has been demonstrated in murine models—depletion of Foxp3+CD4+ Treg cells resulted in severe autoimmunity, allergy, and immunopathology (e.g., IPEX) in otherwise normal animals and those same diseases can be prevented by reconstituting Treg cells." (PMID 35207219, 2022). "Thanks to the obtained results, the researchers showed that CD4+CD25HIGHFoxp3+ cell homeostasis is disturbed in patients with CVID, especially in the presence of autoimmunity, which may indicate that Treg lymphocytes are involved in the pathological mechanisms of CVID." (PMID 35207219, 2022). "Similar to CD4+ and CD8+ T cells, the DDR mechanisms in Tregs are receiving increased attention since these cells have a pivotal role in the tumor microenvironment where DNA damage usually precedes, and in preventing autoimmunity where the DDR’s role is currently emerging." (PMID 34072535, 2021). "We demonstrate that CD8+ T effector memory cells might drive and sustain autoimmunity via macrophage migration inhibitory factor (MIF)‐CD74 signaling to immature B cells and CC‐chemokine ligand 5 (CCL5)‐mediated recruitment of cytotoxic CD4+ T cells." (PMID 34254741, 2021). "In participants with T1D ≤ 3 months, AB‐negative and AB‐positive FDR, the increased islet‐specific CD4+ T‐cell autoimmunity presumably indicates ongoing priming of immune cells and epitope spreading to multiple β‐cell antigens prior to, or soon after the clinical manifestation of disease." (PMID 34336205, 2021). "The dynamics of regulatory cells may also be of interest, especially for autoimmunity, and it is possible, but not known, whether these cells will follow the same pattern as the CD4+ T cells in rhinovirus infection." (PMID 34350827, 2021). "It has been shown that the deficiency in CD4+CD25+ regulatory cells is important because SCID mice transferred with CD4+CD25− T cells also developed colitis, and this autoimmunity could be prevented by providing CD4+CD25+ cells within 10 days of CD4+CD25− T cell transfer." (PMID 33923792, 2021). "Tfh are a subset of CD4+ T cells in the germinal center that express CXCR5 and provide help to B cells for antibody production; circulating Tfh (cTfh) are considered a counterpart of Tfh, and alterations in the frequency of cTfh have been described in several autoimmune conditions." (PMID 35087513, 2021).
Autoimmunity (continued). "Consistent with this, a previous transcriptomic study using microarrays postulated that gene signatures from CD8+ but not CD4+ T cells, could predict long-term prognosis in several autoimmune conditions including SLE34." (PMID 33790300, 2021). "Because CD4+ T cells play a central role in autoimmunity, and CD226 promotes self-reactive CD4+ T cell activation in the autoimmune response, we considered whether CD226 functions by altering the balance of CD4+ T cell subsets involved in the pathogenesis of EAE." (PMID 32983109, 2020). "It is important to note that the observed immune-regulatory effect of CD8+ T cells on CD4+ T cell activation is not per se surprising as a similar effect has been shown in humans and murine models of autoimmunity, transplant rejection, and anti-tumor immune responses." (PMID 32941545, 2020). "The lack of autoimmunity and polyclonal B cell activation in CD4.Ezh2-KO T cell-induced cGVHD could be due to T cell unresponsiveness, T cell failure to stimulate B cell responses, or a failure of activate autoreactive B cells." (PMID 32503684, 2020). "Interestingly, while mice with MALT1-deficient Tregs and mice with enzymatically-dead MALT1 in Tregs both developed autoimmune-like wasting disease, only full MALT1-KO in Tregs reduced splenic Treg frequencies and increased IFNg/IL17 production in conventional CD4 T cells." (PMID 32870913, 2020). "In addition to its role in exhaustion, PD-1 is expressed in memory phenotype (MP), but not naïve, CD4 T cells in the steady state and plays an important role in peripheral tolerance and the prevention of autoimmunity in mouse models." (PMID 32709717, 2020). "Impaired T-cell receptor–mediated proliferation and hyper-inflammation of MP CD4 T cells have also been found in SLE and RA patients further indicating that maintenance of MP T-cell homeostasis is essential for both preventing autoimmunity and supporting adaptive immune responses." (PMID 32709717, 2020). "Furthermore, other motifs of TF complexes important to T cell biology, such as the BAFT-JUN-AP1 complex, shown to play a role in CD4+ T cell differentiation, and TFs of the ETS family, whose deletion in CD4+ T cells result in autoimmunity in mice, were enriched in the hypomethylated cluster." (PMID 32977850, 2020). "Immunostaining of spleen sections revealed that the number of GCs was significantly increased in CD4-ERα KO female mice compared with wild-type mice, suggesting that ERα in T cells possibly regulates spontaneous induction of TFH responses and autoantibody production to prevent autoimmunity." (PMID 30988419, 2019). "Overall, the data presented in this study indicate that CD8+HLA-DR+ Treg and CD4+FOXP3+ Treg share phenotypic and functional features, which may provide cues to similar involvements in the control of antitumor immune responses and autoimmunity." (PMID 30555473, 2018). "Furthermore, excellent antitumor immune responses can also be achieved using combinations of Abs that block CTLA4, PD1, OX40, and CD30 ligands, without CD4 T cell–driven autoimmunity." (PMID 28646041, 2017). "This raised the possibility that blocking OX40 and CD30 signaling could attenuate CD4-driven autoimmunity without compromising CD8 antitumor responses." (PMID 28646041, 2017). "However, no overt autoimmunity was noted and the reduction in CD4 ICOS levels does not support ongoing T cell activation." (PMID 28646160, 2017). "Thus, we demonstrated that GAG ameliorated autoimmune T1DM by upregulating both CD4+FoxP3+ and CD8+CD122+PD-1+ Tregs while GAG synergized with CsA to further suppress autoimmunity and T1DM by reversing the decline in CD4+FoxP3+ Tregs resulted from CsA treatments." (PMID 28947964, 2017).
Autoimmunity (continued). "Incomplete DT-mediated Foxp3+ Treg depletion in naive adult DEREG mice is advantageous to our studies as it enables a window to study effects of Foxp3+ Treg ablation on myelin reactive CD4+ T cells without confounding complications of lymphoproliferative disease and systemic lethal autoimmunity." (PMID 27708643, 2016). "Of interest, frequencies of insulin mimetope-specific Foxp3+Tregs were significantly lower in children with recent onset of autoimmunity than in children without autoimmunity (no autoimmunity versus recent onset of autoimmunity: 1.9±0.9 versus 0.5±0.4% of Tet+CD4+T cells, P<0.05)." (PMID 26975663, 2016). "Conversion of naive and polarized CD4+ T cells to cCD4+ T cells and induction of apoptosis in antigen-presenting cells might not be sufficient to suppress autoimmunity." (PMID 26973647, 2016). "We further found that 20% of memory CD4+ T cells responding to the GAD65247-266 peptide share identical T cell receptors to T cells responding to the CVB4 p2C30-51 peptide, thereby providing direct evidence for the potential of molecular mimicry as a mechanism for GAD autoimmunity." (PMID 27604323, 2016). "The CD4+CD25−CD161+ T effector cells do not possess suppressive function and might be pathogenic in autoimmune conditions due to their IL-17 production; however, there is no clinical and experimental data directly addressing this point." (PMID 26436101, 2015). "Indeed, we showed that HER-3 reactive CD4 T cells existed in HNSCC patients without any clinical signs of autoimmunity." (PMID 26538233, 2015). "In models of autoimmunity, H. polygyrus infection has been shown to be suppressive in the experimental autoimmune encephalomyelitis (EAE) model of multiple sclerosis 9, and suppression can be transferred with either CD4+ T cells or CD19+ B cells from infected mice." (PMID 25867600, 2015). "However, our studies in FoxP3KOOX40CD30KO mice suggest that that CD4 mediated immunity can be obviated in FoxP3KO without seriously compromising autoimmunity." (PMID 24782861, 2014). "Second, and in contrast, adoptive transfer of CD4+Foxp3+CD25+ Treg-delayed disease progression and significantly reduced mortality in mice with already established disease, indicating that, depending on a sufficient amount, Treg are able to counteract even chronically active autoimmunity." (PMID 23446139, 2013). "Complementary to its impact on CD4+ T-cell CNS autoimmunity and myelin repair, our findings further suggest that HGF treatment could be exploited to control CD8+ T-cell-mediated, MHC I-restricted autoimmune dysfunctions such as MS." (PMID 24344806, 2013). "Notably, these CD4+ and CD8αα+TCRαβ+ T cells are involved in the negative feed back regulation of autoimmunity." (PMID 21450109, 2011). "These included CD4+ count and HIV load in HIV-positive patients, relapse and complication rate in cancer patients, allograft rejection rate in transplant patients, disease activity scores in patients with autoimmune conditions and lung function tests in respiratory patients." (PMID 22216224, 2011). "Importantly, the cotransfer of naïve HA-specific CD8+ and CD4+ T cells into lymphoreplete InsHA mice did not result in autoimmunity and CD8+ T cells were tolerized under these conditions." (PMID 20856822, 2010). "In the mouse system, CD25+CD4+ regulatory T cells suppress the activation and proliferation of other CD4+ and CD8+ T cells specific for auto antigens which of course is important to prevent autoimmunity but on the other hand prevents the effective generation of immunity to tumor antigens." (PMID 16164749, 2005). "Studies have shown that patients with CVID and autoimmune manifestations often exhibit altered CD4+/CD8+ T-cell ratios along with reduced regulatory T cells, indicating that T cell imbalance may contribute to immune dysregulation and the development of autoimmunity." (PMID 40993545, 2025). "CXCR3− CCR6+ cTfh cells in IRs may suggest their role in autoimmunity, rather than CD4+ recovery." (PMID 40130906, 2025).
Autoimmunity (continued). "Moreover, CD4+ T cells from neuropathic mice are sufficient to transfer SAPP to immunodeficient recipients, and a myelin-specific CD4+ TCR–transgenic mouse model spontaneously develops autoimmune peripheral neuropathy, suggesting that CD4+ T cells are sufficient for the development of autoimmunity." (PMID 39087473, 2024). "Therefore, while NK cell dampening of CD4+ T cell responses might be beneficial in some contexts (autoimmunity, immunopathology), it can also have long-term negative effects (including viral persistence) and result in a reduced T cell memory pool." (PMID 36719466, 2023). "We provide evidence that a small subset of CD4+IL-6R+ TEM cells from carriers of the “non-risk/CC’ genotype show higher sensitivity to FAS agonist-induced expression of early apoptotic markers (Annexin V+ cells), potentially leading to decreased survival of pathogenic T cells in autoimmunity." (PMID 35911690, 2022). "To investigate the mechanism behind accelerated onset and progression of autoimmunity in SfTCRminiAbEp mice we hypothesized that when the same class II MHC/peptide complexes are abundant in the thymus and the periphery, more autoreactive CD4+ cells require suppression by Tregs." (PMID 31653839, 2019). "However, note that in humans, haploinsufficiency of CTLA4 is associated with significant autoimmunity, so blockade of CTLA4 could act synergistically with Treg depletion to promote the CD4-driven autoimmunity seen in mice and humans lacking Tregs." (PMID 28646041, 2017). "However, it will be interesting to determine how autoreactive CD4 T cells are prevented from being activated by the presentation of antigens derived from apoptotic cells as this likely prevents the subsequent activation of autoreactive CD8 T cells and autoimmunity." (PMID 28257518, 2017). "Notably, TCR Vβ7 CD4+ precursors were deleted by HERV-K18 in an in vitro model of human negative selection, altogether linking glucocorticoid-induced transcription of endogenous retroviruses, TCR Vβ repertoire selection and autoimmunity also in the human system." (PMID 29181000, 2017). "Moreover, a combination of ins.mim.1=14E-21G-22E and ins.mim.4=14E-21E-22E resulted in significantly enhanced stimulation when compared with ins.mim.2=21G-22E and ins.mim.3=21E-22E) either in CD4+T cells from non-diabetic children with ongoing islet autoimmunity (P<0.01) or without autoimmunity." (PMID 26975663, 2016). "CD4+ T follicular helper cells (TFH) were assessed in adult patients with common variable immune deficiency (CVID) classified according to the presence of granulomatous disease (GD), autoimmunity (AI), or both GD and AI (Group I) or the absence of AI and GD (Group II)." (PMID 27069935, 2016). "In a recent study, CD19+CD24hiCD38hi Bregs from patients with SLE were found to be refractory to CD40 engagement and produced less IL-10 and lacked CD4+ T-cell suppressive capacity compared with the healthy controls, suggesting that functional defects of Bregs could lead to autoimmunity." (PMID 26209442, 2015). "Most circulating and intrahepatic PD-1hiICOShi CD4+ Tfh1-like cells did not express CXCR5 and therefore resembled CXCR5–CXCL13+ peripheral helper cells that infiltrate tumors and tissues inflamed by autoimmunity." (PMID 40956619, 2025). "A large proportion of CD4+ T cells that expressed GM-CSF also expressed CXCR6, but this chemokine receptor did not play a main role in the CNS autoimmunity." (PMID 40904462, 2025). "We further confirmed that MP CD4+ T cells did not respond to the MOG33-55 antigen, indicating the innate-like functions of CCR6high MP CD4+ T cells in autoimmune neuroinflammation." (PMID 37121980, 2023). "CD57 and KLRG1 are commonly used as senescence markers in CD4+ and CD8+ T cells to assess T cells fitness after Ebola vaccination, in cancer or autoimmunity, but their relevance in Tregs is not well defined." (PMID 35931871, 2023).